IGSF8 (immunoglobulin superfamily member 8)
Diseases named in the same sentence as IGSF8 in open-access papers:
IGSF8 is named in the same sentence as 29 diseases in open-access papers, as found by Europe PMC text mining. Sharing a sentence is not in itself a finding about the gene and the disease. The quoted sentences say what the papers report.
melanoma (10 papers, 2012 to 2025). A malignant, usually aggressive tumor composed of atypical, neoplastic melanocytes. "In certain solid tumors such as melanoma, lung, prostate cancer, and glioma, IGSF8 was shown to suppress tumor progression by modulating pathways like TGF-β and EGFR-MAPK, thereby inhibiting proliferation and metastasis." (PMID 40936932, 2025). "In contrast, the proteins that were enriched in the exosomes of SK-MEL-28 and MeWo melanoma cell lines included p120 catenin, radixin, and immunoglobulin superfamily member 8 (PGRL)." (PMID 27941674, 2016). "They discovered several novel melanoma exosomal proteins, such as p120 catenin, radixin, and immunoglobulin superfamily member 8 (PGRL)." (PMID 23056502, 2012). "Furthermore, studies have shown that IGSF8 may contribute to the progression of melanoma by negatively regulating TGF-β signaling, further demonstrating its involvement in tumor growth and metastasis." (PMID 40936932, 2025).
prostate carcinoma (5 papers, 2015 to 2025). A carcinoma that arises from epithelial cells of the prostate gland. "Additionally, in vitro experiments have demonstrated that IGSF8 expression is associated with the growth of androgen-deficient prostate cancer cells." (PMID 40936932, 2025). "We found that IGSF8 expression was downregulated in prostate cancer cells after transfection of the three shRNAs using the RT-qPCR assay." (PMID 40936932, 2025). "The effects of IGSF8 appear to be mediated through its interaction with a tetraspanin protein, CD9, previously implicated in prostate cancer progression." (PMID 26036626, 2015). "IGSF8 is amplified in a majority of cancer types, except prostate cancers, where homozygous deletions were detected in 2% of analyzed samples (in 5 out of 244 samples of prostate adenocarcinomas)." (PMID 26036626, 2015). "Knockdown of IGSF8 significantly inhibited the proliferation ability of prostate cancer cells." (PMID 40936932, 2025). "It seems likely that, in spite of the rarity of IGSF8 deletion in prostate cancers, the level of IGSF8 protein may also be reduced in prostate tumors by epigenetic mechanisms." (PMID 26036626, 2015). "In prostate cancer, CD9 has been identified as a candidate gene involved in androgen-deprived cell proliferation through its interaction with IGSF8, suggesting a role of CD9 itself in AR-mediated prostate cancer progression." (PMID 28881726, 2017). "Remarkably, homozygous deletions of IGSF8 are found almost exclusively in prostate cancers but not in other cancer types." (PMID 26036626, 2015).
glioma (3 papers, 2015 to 2025). A benign or malignant brain and spinal cord tumor that arises from glial cells (astrocytes, oligodendrocytes, ependymal cells). "IGSF8’s association with these mutations hints at a role in DNA repair mechanisms or in controlling glioma cell differentiation and survival, particularly in the context of these chromatin and genome stability regulators." (PMID 40936932, 2025). "In gliomas, IGSF8 has been recognized as a potential therapeutic target due to its role in enhancing tumor cell invasiveness and resistance to conventional treatments, making it a critical factor in glioma progression." (PMID 40936932, 2025). "Specifically, In Glioma (GBMLGG) and BRCA, we observed that IGSF8 expression levels were negatively correlated with most of the immunoregulatory genes." (PMID 40936932, 2025).
ovarian carcinoma (3 papers, 2023 to 2025). A malignant neoplasm originating from the surface ovarian epithelium. "Our group has previously reported IGSF8 as a potential biomarker of ovarian cancer–derived EVs for early detection and it is possible that chronic stimulation with ovarian cancer–derived EVs triggers IGSF8 release from neighboring cells as well." (PMID 40689422, 2025). "Although research in the field of cancer is limited, some studies have indicated that IGSF8 expression may serve as a biomarker for ovarian cancer." (PMID 40936932, 2025). "Using the linear combination of IGSF8 and ITGA5 on the ovarian cancer (n = 10) and healthy control samples (n = 20) on this specificity data set, we achieved a PPV of 15.3% with a sensitivity of 0.90 at specificity of 99.8%, confirming the reliability of our original marker set." (PMID 37884576, 2023).
pancreatic cancer (2 papers, 2023). "Interestingly, neither IGSF8 nor MYOF have been previously implicated in HGSOC or fallopian tube biology but MYOF in EVs from breast and pancreatic cancer cell lines has been shown to contribute to cancer progression via metastasis." (PMID 37205573, 2023).
acute myeloid leukemia (1 paper, 2025). Acute myeloid leukemia (AML) is a group of neoplasms arising from precursor cells committed to the myeloid cell-line differentiation. "In contrast, in hematological malignancies such as acute myeloid leukemia, IGSF8 sustains leukemic stemness by stabilizing β-catenin, preventing its degradation and enhancing Wnt pathway activation, which in turn promotes therapy resistance and disease progression." (PMID 40936932, 2025). "IGSF8 was significantly upregulated in 23 types of cancers and associated with poor prognosis in several cancers, including cell carcinoma and endocervical adenocarcinoma (CESC) and Acute Myeloid Leukemia(LAML)." (PMID 40936932, 2025).
cervical squamous cell carcinoma (1 paper, 2025). A squamous cell carcinoma arising from the cervical epithelium. "In terms of OS, we observed a significant association between high expression of IGSF8 and poor prognosis in several cancer types, including Cervical squamous cell carcinoma and endocervical adenocarcinoma (CESC) and LAML." (PMID 40936932, 2025).
glioblastoma (1 paper, 2015). The most malignant astrocytic tumor (WHO grade IV). "Tumor suppressor activities of IGSF8 have been previously addressed in PCa, although with respect to cell motility rather than AR signaling, and in glioblastomas." (PMID 26036626, 2015).
HCMV infection (1 paper, 2015). "We show that BTN2A1 and IGSF8, two cell surface proteins that belong to the immunoglobulin (Ig) superfamily are degraded during HCMV infection." (PMID 26599541, 2015). "These experiments demonstrated that BTN2A1 and IGSF8 are targeted for degradation since their protein levels were downregulated during HCMV infection, whereas the levels of the GFP which was expressed from the same transcript was elevated." (PMID 26599541, 2015). "We reveal here that BTN2A1 and IGSF8, members of the Ig superfamily, are degraded during HCMV infection." (PMID 26599541, 2015). "Real-time PCR measurements from cell lysates along HCMV infection supported elevation in BTN2A1 and IGSF8 mRNA levels." (PMID 26599541, 2015).
liver cancer (1 paper, 2025). An epithelial or non-epithelial malignant neoplasm that arises from the liver. "The connection between IGSF8 and CTNNB1 mutations in liver cancer suggests that IGSF8 could influence the regulation of Wnt signaling, possibly affecting tumor cell growth or differentiation." (PMID 40936932, 2025).
Obesity (1 paper, 2022). Accumulation of substantial excess body fat. "Comparing the body weight of AAV-injected Sim1-cre mice versus AAV-injected wild-type littermates, we found that overexpression of Snca and Igsf8 caused an exacerbation of HFD-induced obesity, whereas overexpression of Spata2, Pole4, Fndc4, Smim12, or Arrb1 had no impact on body weight." (PMID 36175420, 2022). "Additional studies are also needed to test whether variants in the loci surrounding IGSF8 and SNCA are associated with anthropometric and/or metabolic traits and whether rare variants in these genes are associated with obesity in clinical cohorts." (PMID 36175420, 2022).
parasite infection (1 paper, 2023). "We found Igsf8 as the only shared marker gene between LPS stimulation and PTG parasite infection." (PMID 37575232, 2023).
prostate tumors (1 paper, 2015). "Both CD9 translocations and IGSF8 deletions are observed in 2–3% of prostate tumors." (PMID 26036626, 2015). "This is supported by evidence of IGSF8 deletions in prostate tumors." (PMID 26036626, 2015).
thymoma (1 paper, 2025). A neoplasm arising from the epithelial cells of the thymus. "In terms of RNA methylation, we found that IGSF8 expression was closely associated with multiple m1A, m5C and m6A modification in KIRC, KIRP, ACC and thymoma (THYM)." (PMID 40936932, 2025).
tumor (13 papers, 2015 to 2025). "In this study, we utilized several public databases to investigate the biological role of IGSF8, focusing on its associations with prognosis, tumor heterogeneity, stemness, immune checkpoint genes, and immune cell infiltration across different types of cancer." (PMID 40936932, 2025). "We demonstrate that IGSF8 expression is associated with unfavorable prognosis, enhanced tumor cell proliferation, and suppression of immune infiltration in several malignancies." (PMID 40936932, 2025). "For the tumor immune microenvironment analysis, our findings indicated that the expression levels of IGSF8 in various cancer types were associated with multiple immune regulatory genes and immune checkpoint genes." (PMID 40936932, 2025). "IGSF8 was also closely associated with multiple indicators of tumor heterogeneity, stemness, as well as significant RNA methylation modifications across various cancers." (PMID 40936932, 2025). "The correlation between IGSF8 expression and these mutations suggests that IGSF8 may modulate these critical pathways, potentially affecting tumor proliferation or response to targeted therapies." (PMID 40936932, 2025). "Overall, the mutation landscape analysis suggests that IGSF8 might act as a modulator of oncogenic pathways, influencing tumor progression and potentially serving as a biomarker for identifying mutation-driven therapeutic targets." (PMID 40936932, 2025). "First, although preliminary in vitro experiments confirmed the biological effects of IGSF8, further in vivo validation is essential to clarify its mechanistic role in tumor progression and therapeutic modulation." (PMID 40936932, 2025). "These analyses identify R3HDM4 as a critical oncogenic driver in KIRC, potentially acting through two mechanisms: promoting tumor growth and metastasis while also exerting immunomodulatory effects, possibly mediated by IGSF8." (PMID 41346582, 2025). "This study investigated the correlation between IGSF8 expression levels and immune regulatory genes, immune checkpoints, and tumor-infiltrating cells." (PMID 40936932, 2025). "Emerging evidence suggests that IGSF8 plays a significant role in various cancers by influencing tumor progression through regulation of cell proliferation, migration, and apoptosis." (PMID 40936932, 2025). "Intriguingly, IGSF8 exhibits dual roles in tumor biology, acting either as a tumor suppressor or a tumor promoter depending on the cellular context." (PMID 40936932, 2025). "Other immune-related proteins found in hFTE-derived EVs include IGSF8, which is frequently overexpressed in tumor cells with antigen presentation defects and acts as a suppressor of NK cells." (PMID 40689422, 2025). "We further investigated the correlation between the expression level of IGSF8 and tumor heterogeneity and stemness." (PMID 40936932, 2025). "This expanded understanding of IGSF8’s function underscores the necessity for further exploration of its role as a critical mediator in tumor biology and immune evasion." (PMID 40936932, 2025). ", MHC genes, IGSF8 (immune adhesion/tumor immunity), TMB, and MSI (genomic instability/ICI response markers)." (PMID 41346582, 2025). "Recent studies have demonstrated that the novel IC molecule IGSF8 is expressed on tumor cell surfaces and forms specific interactions with KIR3DL2 receptors on human NK cell surfaces and Klra9 receptors in mice." (PMID 40463500, 2025). "We observed a significant correlation between IGSF8 expression and tumor purity in 25 types of tumors, with 23 showing a significant positive correlation and 2 showing a significant negative correlation." (PMID 40936932, 2025). "Moreover, IGSF8 has emerged as an innate immune checkpoint molecule in the tumor microenvironment (TME)." (PMID 40936932, 2025). "Furthermore, we observed a correlation between IGSF8 expression and advanced age across multiple tumor types." (PMID 40936932, 2025).
tumor (continued). "Importantly, these findings highlight IGSF8’s dual role as both an oncogenic driver and an immune regulator, positioning it as a central modulator of tumor progression and immune evasion." (PMID 40936932, 2025). "Unlike previous research, which has primarily focused on specific cancers, our study provides a comprehensive overview of IGSF8’s dual role in promoting tumor growth and modulating immune responses, suggesting its potential as a universal therapeutic target in cancer." (PMID 40936932, 2025). "Therefore, the impact of IGSF8 on prognosis may not only reflect its intrinsic roles in tumor signaling and stemness, but also its influence on shaping immune landscapes across different cancer types." (PMID 40936932, 2025). "The association with IGSF8 may support immune cell recruitment and activation at inflammatory or tumor sites, whereas negative associations with CTLA4 and TIGIT imply a counter-regulatory effect on checkpoint pathways, potentially strengthening T-cell-mediated anti-tumor responses." (PMID 41180485, 2025). "Additionally, the IGSF8.06 antibody targeting IGSF8 and NK cell-related receptors, when administered in combination with anti-PD-1 or anti-PD-L1 antibodies, can effectively inhibit immune evasion and therapeutic resistance resulting from tumor cells down-regulating antigen presentation." (PMID 40463500, 2025). "From a therapeutic standpoint, co-targeting IGSF8 and CD276 may provide synergistic benefits by simultaneously enhancing T and NK cell activity and reversing tumor immune evasion." (PMID 40936932, 2025). "For example, the correlation of CDH1 mutations to the activation of WNT, EGFR, and AKT pathways as well as the inactivation of tumor suppressors, such as EPHB3 and IGSF8, provides several hypotheses to test." (PMID 29520031, 2018).
cancer (10 papers, 2015 to 2025). A tumor composed of atypical neoplastic, often pleomorphic cells that invade other tissues. "IGSF8 alteration was observed in 22 cancers, with a mutation frequency of 4.0% for UCEC, 2.7% for DLBC, 2.2% for LUAD and 2.1% for COAD." (PMID 40936932, 2025). "In five different types of cancer, we divided patients into high-expression and low-expression groups based on the median expression level of IGSF8 and compared the differences in the mutation landscape between the two expression groups." (PMID 40936932, 2025). "We found in GBMLGG, IGSF8 expression levels were negatively associated with cancer associated fibroblasts (CAFs), macrophages, NK cells and positively associated with B cells and CD4+ T cells." (PMID 40936932, 2025). "The analysis of the mutation landscape across different cancer types, based on IGSF8 expression levels, shows distinct patterns of gene mutations." (PMID 40936932, 2025). "Recent studies have linked IGSF8 dysregulation to the pathogenesis of various diseases, including neurological disorders and cancers." (PMID 40936932, 2025). "To fill this knowledge gap, we conducted a systematic investigation using The Cancer Genome Atlas (TCGA) data to examine the expression, prognostic relevance, immune associations, and therapeutic implications of IGSF8 across a wide range of human cancers." (PMID 40936932, 2025). "In addition, IGSF8 expression was associated with shifts in stromal components such as cancer-associated fibroblasts and macrophages, further indicating its influence on both structural and immunological features of the TME." (PMID 40936932, 2025). "The current study builds upon these findings by conducting a pan-cancer analysis of IGSF8, revealing its broader oncogenic role across multiple cancer types." (PMID 40936932, 2025). "In summary, this study provides a comprehensive characterization of IGSF8 across multiple cancer types, integrating transcriptomic data analysis with preliminary in vitro validation." (PMID 40936932, 2025). "In the context of oncology, IGSF8 has gained attention due to its oncogenic potential across various cancer types." (PMID 40936932, 2025). "Recent studies have unveiled that IGSF8 is highly expressed in several cancer types, where it significantly modulates the immune microenvironment by interacting with key immune cells like natural killer (NK) cells and dendritic cells (DCs)." (PMID 38881902, 2024). "IGSF8 (Immunoglobulin superfamily member 8, also known as CD316 or EWI-2) plays a pivotal role as an innate immune checkpoint in cancer immunology." (PMID 38881902, 2024). "Potential alterations of the IGSF8 gene across various human cancers were analyzed using cBioPortal." (PMID 26036626, 2015). "Many AR targets affected by IGSF8 knockdown are known positive and negative regulators of cancer cell proliferation and survival." (PMID 26036626, 2015). "Our findings indicated that IGSF8 might be used as a potential prognostic marker and therapeutic target for various cancers." (PMID 40936932, 2025). "This suggests that IGSF8 may be involved in regulating specific oncogenic pathways in different cancers." (PMID 40936932, 2025). "Despite these emerging insights, a comprehensive pan-cancer evaluation of IGSF8 remains lacking." (PMID 40936932, 2025).
infection (3 papers, 2014 to 2023). The state of being infected such as from the introduction of a foreign agent such as serum, vaccine, antigenic substance or organism. "These cells were then infected with HCMV and the kinetics of BTN2A1 and IGSF8 expression along infection was evaluated by western blot analysis." (PMID 26599541, 2015). "In order to test if these proteins are involved in IGSF8 degradation, we tested the expression of IGSF8 during infection with AD169VarL-BAC derived virus in which US9 or UL40 were deleted." (PMID 26599541, 2015). "We next tested the expression of BTN2A1 and IGSF8 during infection with the AD169VarL virus and a BAC derived AD169VarL virus, in which the US2-US6 region was deleted (the region in which the BAC cassette was inserted)." (PMID 26599541, 2015).
IGSF8 also shares sentences with these, for which no sentence is quoted: brain tumor (1 paper); breast carcinoma (1); endocervical adenocarcinoma (1); epidermoid carcinoma (1); epilepsy (1); HIV-1 infection (1); Impaired glucose tolerance (1); leukaemia (1); lung adenocarcinoma (1); malignant glioma (1); prostate adenocarcinoma (1); viral infection (1).